RBFOX2 (RNA binding fox-1 homolog 2)
Description:
RNA-binding protein that regulates alternative splicing events by binding to 5'-UGCAUGU-3' elements. Prevents binding of U2AF2 to the 3'-splice site. Regulates alternative splicing of tissue-specific exons and of differentially spliced exons during erythropoiesis (By similarity). RNA-binding protein that seems to act as a coregulatory factor of ER-alpha. Together with RNA binding proteins RBPMS and MBNL1/2, activates vascular smooth muscle cells alternative splicing events.
Synonyms: FOX2; HRNBP2; RBM9; RTA; HNRBP2; FOX-2; dJ106I20.3; fxh
Tractability: PROTAC: ubiquitination databases record sites on it; its protein half-life has been measured.
Gene: Protein-coding gene on chromosome 22 (35,738,736 to 36,028,824, reverse strand). Ensembl gene ENSG00000100320.
Subcellular location: Nucleus; Cytoplasm
Subcellular location (Human Protein Atlas): Nucleoplasm
Pathways (Reactome):
Signal Transduction: FGFR2 alternative splicing
Gene Ontology:
Molecular function: DNA-binding transcription factor binding; protein binding; RNA binding; transcription corepressor activity; mRNA binding; nucleic acid binding
Biological process: estrogen receptor signaling pathway; negative regulation of DNA-templated transcription; nervous system development; regulation of alternative mRNA splicing, via spliceosome; regulation of cell population proliferation; RNA metabolic process; regulation of RNA splicing
Cellular component: nucleoplasm; nucleus; cytoplasm
Genetic constraint (gnomAD): Loss-of-function variants: 9 observed, 46.73 expected, observed/expected ratio (o/e) 0.19, 90% interval 0.12 to 0.34. The upper end of that interval is the gene's LOEUF score, 0.34, which puts it in group 1 of 6, group 1 being the genes least tolerant of losing a copy. Missense variants: 313 observed, 465.63 expected, observed/expected ratio (o/e) 0.67, 90% interval 0.61 to 0.74. Synonymous variants: 175 observed, 184.97 expected, observed/expected ratio (o/e) 0.95, 90% interval 0.84 to 1.07.
Gene-disease validity (ClinGen):
ClinGen rates the evidence that RBFOX2 causes each of these diseases.
congenital heart disease (autosomal dominant): Strong. A heart disease that is present at birth.
Homologues: Orthologues: chimpanzee RBFOX2 (99% identical), pig RBFOX2 (98% identical), mouse Rbfox2 (96% identical), rat Rbfox2 (93% identical), macaque RBFOX2 (87% identical), dog RBFOX2 (86% identical), rabbit RBFOX2 (79% identical), tropical clawed frog rbfox2 (73% identical), guinea pig RBFOX2 (72% identical), Drosophila melanogaster Rbfox1 (41% identical), zebrafish rbfox2 (40% identical), Caenorhabditis elegans fox-1 (30% identical). Paralogues in human: RBFOX1 (57% identical), RBFOX3 (49% identical).
Diseases named in the same sentence as RBFOX2 in open-access papers:
RBFOX2 is named in the same sentence as 97 diseases in open-access papers, as found by Europe PMC text mining. Sharing a sentence is not in itself a finding about the gene and the disease. The quoted sentences say what the papers report.
breast cancer (23 papers, 2010 to 2025). A primary or metastatic malignant neoplasm involving the breast. "In fact, the association of low ESRP1/ RBFOX2 ratio with high risk of metastasis in early breast cancer was speculated to be a new early prognostic marker of breast cancer metastasis." (PMID 31737791, 2019). "RBFOX2 transcriptionally represses ESRP1, and the ratio of ESRP1 and RBFOX2 determines the alternative splicing of hMENA in breast cancer." (PMID 38110955, 2023). "RBFOX2 has been described as an important regulator of EMT splicing signatures in breast cancer and cancer cell line models." (PMID 38114498, 2023). "RBFOX2 promotes oncogenic splice-switching and the resulting mesenchymal signature and drives an invasive phenotype in breast cancer." (PMID 38106992, 2023). "Both cancer types exhibit RBFOX2 downregulation, either by transcriptional control in ovarian cancer or by alternative splicing in breast cancer, resulting in a reduction of the nuclear RBFOX2 isoform." (PMID 38114498, 2023). "Further, RBFOX2 was identified as a key splicing regulator in ovarian and breast cancers responsible for the overlapping exon splicing patterns in these two cancers." (PMID 38114498, 2023). "Downregulation of RBFOX2 resulting in a shift to epithelial phenotype is also observed in breast cancers." (PMID 38002944, 2023). "Among other RBPs such as Elav-like (Elavl) proteins, Staufen1, and RNA binding protein fox-1 homolog 2 (Rbfox2), we found the Pumilio protein family consisting of Pum1 and Pum2 to be highly expressed in glioblastoma, neuroblastoma, and breast cancer cells." (PMID 34445704, 2021). "On the basis of these assumptions, we tested two ratios between the epithelial and mesenchymal specific splicing factors, ESRP1/RBFOX2 and ESRP2/RBFOX2 in an early breast cancer setting." (PMID 27911856, 2017). "RBFOX2 is involved in various diseases and biological processes including congenital heart disease, breast cancer, epithelial-mesenchymal transition and pluripotent stem cell differentiation." (PMID 28316886, 2017). "Depletion of Rbfox2 in mesenchymal cells elicited significant changes in cell morphology and motility and promoted conversion to an epithelial phenotype in breast cancer cells." (PMID 24349438, 2013). "The RBFOX2 splicing factor has recently been demonstrated to regulate subtype-specific splicing in a panel of breast cancer cell lines." (PMID 21876675, 2011). "Recently, it has been suggested that RBFOX2 activity plays a role in regulating a set of breast cancer subtype–specific alternative splicing events." (PMID 21876675, 2011). "Indeed, both QK and RBFOX2 were shown to repress inclusion of the Flnb H1 exon in breast cancer cells but in PAC1 cells all four RBPs are activators of the Flnb exon." (PMID 41428739, 2025). "Furthermore, RBFOX2 expression was found to increase during the acquisition of a mesenchymal phenotype in breast cancer cells." (PMID 38881877, 2024). "Hypoxic-induced exosomal delivery of TGF-β contributes to the elevation of TGF-β signaling, resulting in the regulation of human MENA alternative splicing and promoting EMT in breast cancer via the TGF-β-RBFOX2 (RNA binding Fox-1 homolog 2)-ESRP1 (epithelial splicing regulatory protein 1) axis." (PMID 36233088, 2022). "Interestingly, a switch between RBFOX2 (also called RBM9) and ESRP1/2 splicing factors has been involved in epithelial to mesenchymal transition (EMT), and EMT was previously found associated with Doxo resistance in breast cancer." (PMID 31943118, 2020). "Interestingly, a subset of these RBFOX2 target exons is preferentially excluded across multiple cancers, including lung, breast, and colon; further, these RBFOX2 target exons were shown to be alternatively spliced in ovarian and breast cancers in response to RBFOX28." (PMID 38114498, 2023).
breast cancer (continued). "RBFOX2 plays a dual role, acting as an important co-regulator of ESRP1 in epithelial phenotype cells and as an interstitial-specific splicing factor in more invasive breast cancer subtypes." (PMID 40046628, 2025). "To identify a new early prognostic marker of metastasis, we evaluated EMT-related gene expression in breast cell lines, and in primary tumor tissue from 31 patients with early breast cancer, focusing our attention on EMT-related splicing factors ESRP1, ESRP2 and RBFOX2." (PMID 27911856, 2017). "RBFOX2 plays a dual role in that it is both an important co-regulator of ESRP1 in epithelial phenotype cells and a mesenchymal-specific splicing factor during EMT and in more aggressive breast cancer subtype cell lines." (PMID 27911856, 2017). "Hypoxia-induced TGF-β signaling upregulates SLUG and RBFOX2, which in turn transcriptionally repress ESRP1 expression; furthermore, ESRP1 downregulation promotes the generation of the hMENAΔ11a isoform, which results in the mesenchymal phenotype and thereby promotes breast cancer cell invasion." (PMID 38110955, 2023). "Si-RNA mediated knockdown of RBFOX2 did not alter the level of inclusion of exons v8-v10 into CD44 mRNA in both non-transformed mammary epithelial cell line NMuMG and epithelial murine breast cancer cell line PY2T under normal conditions and TGF-β-treatment." (PMID 38106992, 2023).
ovarian carcinoma (12 papers, 2010 to 2025). A malignant neoplasm originating from the surface ovarian epithelium. "Previous studies have investigated the expression and biological effect of RBFOX2 in some tumors, such as nasopharyngeal carcinoma, endometrial cancer and ovarian cancer." (PMID 38881877, 2024). "Additionally, Malat1 has also been shown to promote ovarian cancer through the regulation of splicing factor RBFOX2." (PMID 40861865, 2025). "The overlapping action of QKI and RBFOX2 in splicing regulation has also been reported in ovarian cancer, and global splicing analysis of eight solid cancer varieties has revealed a high overlap of exons that contained both QKI and RBFOX2 motifs in the flanking introns." (PMID 40207498, 2025). "Knockdown of RBFOX2 significantly upregulation of the KIF1B and increased sensitivity to anoikis in ovarian cancer cells." (PMID 38881877, 2024). "By sponging miR-211, MALAT1 up-regulates PHF19 expression and induces RBFOX2 expression and alternative processing of the tumor suppressor gene KIF1B, leading to ovarian cancer cell proliferation, invasion, increased anoikis, and anchorage-independent growth." (PMID 32174966, 2020). "In ovarian cancer, MALAT1 knockdown decreased proliferation, invasion, anchorage-independent growth, and decreased expression of RNA Binding Fox-1 Homolog 2 (RBFOX2), an RNA-binding protein which regulates alternative splicing events." (PMID 31003545, 2019). "For example, QKI showed enriched eCLIP at RBFOX2 knockdown-excluded exons, and there was significant correlation in splicing changes upon knockdown of RBFOX2 or QKI (R2 = 0.19, P = 1.2 × 10−5), matching previous observations in SKOV3ip1 ovarian cancer cells." (PMID 32728246, 2020).
heart failure (9 papers, 2016 to 2024). Inability of the heart to pump blood at an adequate rate to meet tissue metabolic requirements. "Experimental evidence from various animal models has consistently shown that reduced expression levels of RBFOX2 are associated with a decreased heart rate and structural disarray of myofibrils, and can lead to heart failure." (PMID 39334823, 2024). "Recent studies indicated that dysregulation of Rbfox2 is associated with heart development, heart failure, and cardiac arrhythmias in myotonic dystrophy." (PMID 37415128, 2023). "Mechanistically, RBFox2 regulates numerous altered splicing events linked to specific heart failure phenotypes, which may constitute a key part of the developmental program during postnatal heart remodeling." (PMID 36674797, 2023). "Known as a well-studied splicing factor, Rbfox2 knockout causes heart failure in mice." (PMID 37640841, 2023). "Moreover, our data suggest that HLHS patients with RBFOX2 mutations are more likely to develop heart failure following palliative surgery, suggesting that early transplantation might be critical for this cohort." (PMID 36198703, 2022). "Although it is currently unknown whether RBFOX2 itself becomes secondarily downregulated in the SV myocardium in the absence of RBFOX2 mutations, decreased expression could contribute to early heart failure in a broader population and represent a shared pathway to disease pathogenesis." (PMID 36198703, 2022). "Multiple upregulated cardiac key miRNAs (let‐7f, miR‐16, miR‐200b) in heart failure negatively regulate Rbfox2." (PMID 39243148, 2024). "Antagomir, a synthetic miRNA inhibitor capable of binding to specific miRNAs, has shown promise in ameliorating heart failure characterised by low Rbfox2 expression." (PMID 39243148, 2024). "Increasing mediators have been found to be involved in the pathogenesis of heart failure, including the RNA binding protein RBFox2." (PMID 36674797, 2023). "A further mechanistic study revealed that a cardiac ablation of the RBFox2 protein resulted in transcriptionally induced miRNAs in combination with enhanced miRNAs targeting Jph2, which directly contributed to heart failure." (PMID 36674797, 2023). "RbFox2 heart-specific knockout mice showed an obvious phenotype of heart failure two months after birth, including decreased heart ejection, reduced cardiac contractility, and impaired calcium handling." (PMID 36674797, 2023). "With the aid of Ago2 CLIP-seq data, luciferase assays verified that RBFox2 was targeted by multiple miRNAs, including Let-7, miR-16, and miR-200b, which were significantly upregulated in heart failure." (PMID 36674797, 2023). "The related results indicate that RBFox2 is regulated by multiple miRNAs that are critical for cardiac function during heart failure." (PMID 36674797, 2023). "All these relative results suggest that the RBFox2 protein is a key cardioprotective factor with therapeutic potential for treating heart failure." (PMID 36674797, 2023). "Further studies will be required at the animal level, focused on restoring the RBFox2 protein and exploring disease treatments related to heart failure." (PMID 36674797, 2023). "In all, these findings revealed the molecular mechanism leading to RBFox2 depression in heart failure, and provided an approach to rescue RBFox2 through miRNA inhibition for the treatment of heart failure." (PMID 36674797, 2023). "All these results not only emphasize the protective role of RBFox2 in cardiac function, but also demonstrate its therapeutic potential for heart failure." (PMID 36674797, 2023). "Rbfox2 is known to contribute to heart development, and under pathological conditions, diminished Rbfox2 contributes to pressure-overload-induced heart failure and cardiac decompensation leading to heart failure." (PMID 37415128, 2023). "Expression of Rbfox2 is also decreased in the pressure-overloaded mouse heart, and conditional deletion of Rbfox2 leads to dilated cardiomyopathy and heart failure." (PMID 30051286, 2018).
heart failure (continued). "However, antagomir cocktail therapy has demonstrated the potential to restore Rbfox2 levels in a mouse cardiomyocyte‐induced heart failure model." (PMID 39243148, 2024). "RBFOX2, a regulator of genes critical for cardiac function through alternative splicing, is consistently underexpressed in various animal models, leading to reduced heart rate, disorganized myofibrils, and the development of heart failure." (PMID 39334823, 2024). "Consequently, antagomir presents a potential therapeutic avenue for treating heart failure with a low expression of RBFOX2 phenotype." (PMID 39243148, 2024). "Multiple upregulated miRNAs were confirmed to target RBFox2 in heart failure, which not only suppressed the RBFox2 protein at the post-transcriptional level, but also impaired its protective effects on E–C coupling as well as alternative splicing in cardiomyocytes." (PMID 36674797, 2023). "RBFox2 is expressed from embryo to adult and is greatly reduced in mouse heart failure models." (PMID 36674797, 2023). "The inhibition of miRNAs targeting the RBFox2 protein may serve as an important mechanism for the development of useful drugs for the treatment of heart failure." (PMID 36674797, 2023). "The possible mechanism was that the prolonged incubation of ISO induced NRCMs to develop a severe dysfunction resembling a heart failure phenotype, which depressed RBFox2 and led to the repression of its downstream protein Jph2, and then eventually impaired cardiac E–C coupling." (PMID 36674797, 2023). "Importantly, when the antagomir cocktail was introduced simultaneously with the ISO treatment, the elevation of these heart failure markers and the reduction in the RBFox2 protein was compensated to a level comparable to the negative control." (PMID 36674797, 2023). "Incubation with 100 μM of isoproterenol (ISO) for 6 days resulted in a dramatic induction of heart failure markers (Nppa, Nppb and Tlr4) and a significant reduction in the RBFox2 protein in cultured NRCMs, indicating cardiomyocyte dysfunction after a prolonged ISO treatment." (PMID 36674797, 2023). "Thus, taken together with the results of large-scale upregulation of miRNAs during heart failure, we suggest that RBFox2 is regulated by certain miRNAs at the post-transcriptional level." (PMID 36674797, 2023). "These related results indicate that the inhibition of RBFox2-targeted miRNAs could diminish the ISO-induced upregulation of heart failure markers and rescue the downregulation of the RBfox2 protein." (PMID 36674797, 2023). "In this case, the overexpression of corresponding miRNAs resulted in a ~50% reduction in the RBFox2 protein, which is comparable to previous results from the heart failure stage in the TAC model, whereas direct siRNA interference could repress ~80% of the RBFox2 protein." (PMID 36674797, 2023). "However, it remains unclear how RBFox2 itself is regulated in heart failure." (PMID 36674797, 2023). "Notably, their results confirmed that Rbfox2 deletion leads to DCM, which subsequently causes heart failure, indicating that downregulation of Rbfox2 is not merely a functional consequence of heart failure." (PMID 39243148, 2024). "These miRNAs were significantly upregulated in cardiomyocytes at the heart failure stage after TAC surgery and have been reported to be critical for the regulation of cardiac function, demonstrating that RBFox2 is regulated by multiple cardiac critical miRNAs in heart failure." (PMID 36674797, 2023). "However, a cardiac-specific KO of RBFox2 did not produce a cardiac hypertrophy phenotype during development, indicating that its knockout directly induced a decompensation process leading to heart failure." (PMID 36674797, 2023).